INS (insulin)
Diseases named in the same sentence as INS in open-access papers (continued):
Sharing a sentence is not in itself a finding about the gene and the disease.
diabetes (continued). "The patients were stratified into two subgroups each according to age, sex, BMI, hypertension, dyslipidemia, type of AMI, LVEF, oral hypoglycemic agent use, insulin use, and newly diagnosed diabetes." (PMID 32317703, 2020). "About 80% of the women were overweight and about three out of four women had uncompensated diabetes and were insulin resistant." (PMID 32098332, 2020). "Education (P < 0.001), duration of insulin therapy (P = 0.008), and duration of diabetes (P = 0.014) had significant impact on knowledge level." (PMID 33046046, 2020). "Over 200 million people with diabetes are treated with insulin and this number continues to increase globally." (PMID 33006670, 2020). "A comprehensive review on gender and diabetes identified three major contributors to varying insulin sensitivity between men and women: the activity of estrogen, and differences in adipose tissue distribution and adipokine secretion." (PMID 32787830, 2020). "Because D-Pinitol administration seems to ameliorate the hyperglycemia in some models of diabetes, it has been considered as an insulin mimetic, like other inositols, such as myoinositol and DCI." (PMID 32650579, 2020). "Type 1 diabetes mellitus (T1DM), also known as insulin-dependent diabetes, is classified as a deficiency of insulin secretion." (PMID 33255455, 2020). "It is well known that liver has fundamental importance in regulation of metabolism and insulin sensitivity, as well as diabetes." (PMID 33585009, 2020). "Type 2 diabetes mellitus is characterized by insulin resistance and hypersecretion of insulin from the pancreas to compensate for decreased insulin sensitivity in the peripheral tissues." (PMID 32256145, 2020). "Diabetes is a relevant example, where insulin production is frequently elevated in response to regular highly absorbable carbohydrate intake." (PMID 32983729, 2020). "Patients with type 2 diabetes mellitus (T2D) are unable to secrete sufficient insulin to compensate for increased peripheral insulin resistance." (PMID 32229246, 2020). "When muscle capacity decreases, insulin resistance increases, which can lead to diabetes progression." (PMID 33002067, 2020). "Regarding glucidic metabolism, one patient had elevated insulin and HbA1c levels and was diagnosed with diabetes." (PMID 31924231, 2020). "In subjects with type 2 diabetes mellitus, 10 days of cold acclimation increased peripheral insulin sensitivity by 43%." (PMID 33227979, 2020). "The majority of the participants (87.8%) used antidiabetic drugs, and/or insulin combined with diet and/or exercise to manage their diabetes." (PMID 32503294, 2020). "This is important to understand in regard to diabetes where insulin signaling is disrupted and PKA signaling is dysfunctional." (PMID 32817622, 2020). "Frequent use of insulin is required not only in patients with type 1 diabetes mellitus (T1DM) but also in those with type 2 diabetes mellitus (T2DM) because of poor glycemic control." (PMID 32352017, 2020). "It is very well known that Zn2+ is a crucial factor in the crystallization and storage of insulin, showing a broader impact of zinc on both types of diabetes." (PMID 32987721, 2020). "Type 2 diabetes mellitus (T2DM) is characterized by insulin resistance (IR), which is caused by insufficient production of insulin or by the ineffectiveness of insulin activity to maintain constant blood sugar." (PMID 33335557, 2020). "Recently, it has been reported that septic ICU patients with insulin-treated diabetes have lower adjusted hospital mortality rates and higher peak blood glucose levels when compared to non-insulin-treated patients." (PMID 32160234, 2020). "Insulin secretion plays a central role in the control of blood glucose homeostasis and defects in this process promote the appearance of diabetes mellitus." (PMID 33154349, 2020). "GLUT4 heterozygous knockout mice developed insulin signaling defects in adipocytes with the progression of whole body insulin resistance and diabetes." (PMID 33568989, 2020).
diabetes (continued). "Diabetes mellitus (DM) is a group of metabolic disease characterized by hyperglycemia resulting from defects in insulin secretion, action or both." (PMID 32228598, 2020). "The blood glucose and plasma insulin levels in the diabetes groups were significantly different compared to those in the control group." (PMID 32806520, 2020). "Compared to their peers, participants with stress reported greater diabetes distress, lower diabetes empowerment, greater insulin use, and poorer glycemic control." (PMID 33355538, 2020). "In the management of diabetes, poor diet control, improper treatment of insulin and hypoglycemic drugs, and inadequate patient compliance can lead to increased glucose variability." (PMID 32943002, 2020). "This high rate of editing unlocks the potential to directly model dominant or gain of function alleles identified in humans in founder pigs produced by SSC editing, exemplified by our choice to engineer HNF1a and INS to model dominant forms of diabetes." (PMID 33584819, 2020). "Consistent with existing guidelines, paediatric diabetes clinics should routinely screen for disordered eating behaviours, including insulin omission." (PMID 32128205, 2020). "Phosphorylation is an important regulator of eNOS enzymatic activity in regulation of insulin sensitivity and energy metabolism, suggesting eNOS phosphorylation as a novel target for the treatment of diabetes." (PMID 32106617, 2020). "Diabetes has been identified as one risk factor for HCC, and IRS-1 is an important molecule of the insulin signal transduction pathway of DM." (PMID 32695243, 2020). "In the analysis of concomitant diseases and co-medication, patients with diabetes mellitus (p = 0.049) and concomitant medication with insulin (p = 0.0006) showed a increased LR rate." (PMID 33373378, 2020). "Diabetes mellitus is a common metabolic disorder characterized by the destruction of pancreatic β-cells or diminished secretion and function of insulin." (PMID 32375753, 2020). "We also demonstrated that ghrelin co-localizes with insulin in pancreatic islet cells and that the pattern of ghrelin distribution is altered after the onset of diabetes." (PMID 32325912, 2020). "Mean age in both insulin cohorts was 57 years (overall mean age 57.2 ± 7.9 years), with overall median diabetes duration of 15 years (range 5–34 years) and median MDI duration of 6 years (range 1–18 years), similar in both cohorts." (PMID 31692373, 2020). "Diabetes mellitus, or simply diabetes, is a syndrome characterized by high blood glucose levels that result from defects in the body’s ability to produce and/or use insulin." (PMID 32013271, 2020). "Diabetes mellitus is a group of metabolic disorders that arise from defective action and/or secretion of insulin, resulting in hyperglycemia." (PMID 32349416, 2020). "The first dataset has been generated using the AIDA diabetes simulator which is intended for simulating the effects on the blood glucose profile of changes in insulin and diet for a typical insulin-dependent (type 1) diabetic patient." (PMID 32668724, 2020). "This change is explained by an increase in insulin levels, which were less prominent in patients with impaired glucose tolerance and diabetes." (PMID 31905496, 2020). "Study populations have varied with respect to diabetes characteristics—the time since diagnosis, type of treatment (diet, oral medication, insulin) as well as the presence of various complications from diabetes." (PMID 32168880, 2020). "In other words, this makes pre-diabetes a suitable phase for interventional efforts, such as vitamin E supplementation, to improve the α-tocopherol levels as well as to better the insulin resistance and β-cell function." (PMID 33261162, 2020). "The dysfunction of glucose utilization and metabolism is observed in patients with diabetes due to insufficient INS secretion." (PMID 32425787, 2020).
diabetes (continued). "The oral delivery of insulin is a convenient and safe physiological route of administration for management of diabetes mellitus." (PMID 33120872, 2020). "Higher concentrations of ucOC are associated with enhanced insulin sensitivity and beta-cell function but also correlate with better insulin secretion as well as glycemic control and lower fasting plasma in patients with diabetes." (PMID 32839842, 2020). "The pathological feature of diabetes, hyperglycemia, is a result of an inadequate number and/or function of insulin producing β cells." (PMID 32613468, 2020). "The diabetes frequently relapses (in up to 86% of cases) at the onset of puberty, probably due to the insulin resistance of puberty." (PMID 33102403, 2020). "It is indicated that RBP4 concentrations are elevated in insulin-resistant mice and humans with obesity and diabetes and can be normalized by insulin-sensitizing drugs." (PMID 31956345, 2020). "This study aimed to assess the preliminary safety of a local protocol for intermittent subcutaneous insulin following antenatal betamethasone administration to pregnant women with diabetes in a standard ward at Tygerberg Hospital, South Africa." (PMID 33519707, 2020). "For example, in diabetes, HRs are found to increase in muscle and fat tissues, and this increase correlates with reduced insulin sensitivity in vivo." (PMID 33266015, 2020). "Patients presented with stunted growth and low BMI, and were insulin sensitive; only 15.3% had diabetes onset at ≤15 years." (PMID 32705316, 2020). "The nine patients classified as ASA grade 3 had been diagnosed with cardiac disease (n = 6), chronic renal failure (n = 1), chronic pulmonary disease (n = 1), and diabetes mellitus requiring insulin therapy (n = 1)." (PMID 30920167, 2020). "In terms of the absolute or relative deficiency of insulin secretion in patients with T1DM and severe T2DM, insulin is one of the main and indispensable exogenous drugs in the treatment of diabetes." (PMID 32850735, 2020). "FFAR2 agonists can be used as a new insulin sensitizer for type 2 diabetes mellitus, with therapeutic potential in this disease." (PMID 32411444, 2020). "Diabetes mellitus shows features of hyperglycemia because of absolutely or relatively insufficient serum insulin secretion." (PMID 32038500, 2020). "GLP-1, which is used widely to treat diabetes and obesity, promotes glucose-induced insulin secretion, inhibits glucagon secretion and suppresses the appetite and food intake by slowing gastric emptying and increasing satiety." (PMID 32937828, 2020). "Diabetes is a group of chronic metabolic diseases characterized by hyperglycemia resulting from defects in insulin secretion, insulin action, or both." (PMID 33096670, 2020). "A hypercoagulable state, characterized by a pronounced platelet activation, has been shown in patients with diabetes mellitus; in particular, those with long-lasting disease receiving insulin therapy seem to show a higher tendency to form clots." (PMID 32471222, 2020). "Initiation of CGM in the first month of diabetes diagnosis can allow for more frequent insulin dose adjustments in between visits and education around tighter targets." (PMID 32733375, 2020). "Exogenous insulin therapy is the primary approach for treating diabetes, especially T1DM, and is also sometimes required in cases of advanced T2DM." (PMID 32325974, 2020). "In this study we developed SMA polymeric micelles encapsulating insulin (SMA-insulin) and assessed its biological activity in vitro and in vivo in a diabetes mouse model." (PMID 33120872, 2020). "A glucometer is especially important for patients using insulin injections to manage their diabetes." (PMID 32522187, 2020). "The success of recombinant human insulin as a protein-based therapeutic for the treatment of diabetes mellitus, the first commercially available recombinant protein approved by the U.S. Food and Drug Administration, revolutionized the field of TPPs." (PMID 33352795, 2020).
diabetes (continued). "Obesity and overweight were correlated with a decrease in insulin sensitivity and development of diabetes mellitus type-2, which in turn increase ALT activity." (PMID 32197395, 2020). "The program involved deployment of a DM team consisting of an internist and diabetes specialist nurse to provide consultation at admission, a standardised insulin adjustment scheme, and a glucose monitoring protocol." (PMID 33292816, 2020). "Robustly, we observed significantly decreased insulin-positive cells in the pancreatic islets of all the biochemically diagnosed monkeys with diabetes compared to the normal subjects, confirming the pathologic diagnosis of T2DM." (PMID 32116510, 2020). "Bioactives, such as curcumin, capsaicin, berberine, celastrol, or artemisinin, were shown to improve insulin sensitivity to combat diabetes." (PMID 33042976, 2020). "AP, known as closed-loop control of blood glucose in diabetes, combines a glucose sensor, a control system, and an insulin infusion device (Insulin Pump)." (PMID 32788632, 2020). "Diabetes is a metabolic disease characterized by chronic hyperglycemia as a result of defects in insulin production or insulin sensibility, which will account for more than 592 million cases by 2035 worldwide." (PMID 33276470, 2020). "Vibrating mesh technology has the potential to passively deliver inhaled insulin for effective glycaemic control to treat diabetes." (PMID 32785196, 2020). "Among these are genes associated with insulin (MAX, NUCKS1, PIK3R1, PTPN11), diabetes (PIK3R1) and circadian-related processes (HNRNPU, BHLHE41)." (PMID 34745571, 2020). "Diabetes mellitus is comprised of many metabolic disorders due to mechanisms of failure in insulin secretion or activity, leading to hyperglycemia and other complications." (PMID 32722164, 2020). "These novel findings suggest that targeting mitochondrial Akt is a potential therapeutic approach to enhance cardiac insulin sensitivity in condition such as heart failure, diabetes and obesity." (PMID 33287820, 2020). "With the support of the head of my community health care centre, insulin has now been introduced in our centre, and diabetes patients can now refill their insulin prescriptions here." (PMID 32912234, 2020). "Particularly controversial is the use of new forms of insulin, the so-called insulin analogues, as a new therapy in the treatment of patients with Diabetes Mellitus." (PMID 32002701, 2020). "Diabetes is a global health problem, characterized by defective insulin secretion and resistance to insulin." (PMID 32610588, 2020). "In summary, diabetes inhibited insulin/IRS1/Akt signalling in podocytes, resulting in podocyte apoptosis." (PMID 32238837, 2020). "Adults without a documented CVD who had been prescribed antihypertensive medicines and/or lipid-lowering medicines and/or treatment for diabetes (diet and/oral antidiabetic medicines and/or insulin) were eligible for the survey." (PMID 32197516, 2020). "Individuals with obesity, CKD and T2DM were frequently prescribed RAAS blockade, statins, insulin and sulphonylureas, but infrequently prescribed diabetes therapy with weight‐lowering effects, including GLP1RAs and SGLT2is." (PMID 32845571, 2020). "In patients with diabetes, the ApoM level is significantly reduced, and the rescue of ApoM level can decrease blood sugar level, increases insulin secretion, and improves insulin resistance, thereby serving as a predictor of the development of diabetes." (PMID 33490085, 2020). "In the context of diabetes, various conditions have been proposed to trigger damage to insulin-secreting cells." (PMID 32492936, 2020). "We think that such new findings suggest that the downregulation of PDX-1 expression found in diabetes undermines insulin biosynthesis and secretion which explains, at least in part, the mechanism for β-cell glucose toxicity." (PMID 33322512, 2020).
diabetes (continued). "This study included outpatients with diabetes using insulin who presented at the Department of Diabetes and Metabolism of the Ise Red Cross Hospital." (PMID 32352017, 2020). "A review of the diabetes patient files from 2016 indicates that among the insulin patients, ~ 2/3 received insulin only and ~ 1/3 also received oral treatment." (PMID 32393341, 2020). "Briefly, patients who switched to Gla‐300 insulin had a mean (SD) age at index date was 64.2 ± 11.0 years, 42.5% were female, and 77.5% were included in the diabetes registry for more than 10 years." (PMID 32704550, 2020). "Diabetes mellitus (DM) is a chronic disease caused by relative or absolute insufficiency of insulin secretion, a decrease in insulin sensitivity of target cells or structural defects in insulin itself, resulting in metabolic disorders." (PMID 32266256, 2020). "Resistance to these metabolic actions of insulin (IR) is a major determinant for the development of type 2 diabetes mellitus." (PMID 32566678, 2020). "It has been shown in clinical trials with reduced insulin requirements in children with recent diabetes." (PMID 33153226, 2020). "The case is made for not focusing only on PPG but also of on employing the postprandial insulin assay as a more efficient tool to diagnose prediabetes and diabetes sooner than the current standards." (PMID 32471238, 2020). "Impairments in the insulin signaling pathway leads to insulin resistance, defined as reduced responsiveness of target tissues to circulating levels of insulin, and type 2 diabetes mellitus (T2DM)." (PMID 31906278, 2020). "We observed strong associations between MPV and several medications used to manage diabetes, including insulin, metformin, and sulphonylureas." (PMID 32754618, 2020). "In adult mice, impaired PDX1 expression coincided with changes in beta-cell number and insulin secretion and led to the development of diabetes within 14 days." (PMID 32708678, 2020). "The triglycerides, blood sugar and insulin are considered as remarkable parameters while studying diabetes." (PMID 32971839, 2020). "The costs for insulin treatment are becoming unaffordable, even in developed countries, and the seemingly inexorable global increase in the number of diabetes sufferers who require insulin represents a genuine crisis for many health care systems." (PMID 31378829, 2020). "A lot of contradictory data have been reported in the literature regarding the co-localization of ghrelin with other hormones in the islet of Langerhans, its role in insulin secretion and attenuation of type 2 diabetes mellitus." (PMID 32325912, 2020). "Diabetes medication consumption according to medication groups at baseline was: 71% metformin, 30% sulfonylurea, 14% meglitinides, 8% insulin, 6% TZDs and 1% GLP-1 agonists." (PMID 32933542, 2020). "Cyclin-dependent kinase 5 regulatory subunit-associated protein 1-like 1 (CDKAL1) is one of the strongest diabetes loci identified to date; evidence suggests that it plays an important role in insulin secretion." (PMID 32764395, 2020). "Another study investigated the effect of early time-restricted feeding on blood pressure and insulin sensitivity in men with pre-diabetes." (PMID 33096684, 2020). "In the present study, we evaluated GC-mediated GR action and the insulin signalling pathway in two in vivo and one in vitro model of insulin resistance or diabetes." (PMID 32792855, 2020). "The percentage of insulin-positive areas was lower in wild-type mice with diabetes mellitus than in NFAT5 haploinsufficiency mice with diabetes mellitus." (PMID 33015193, 2020). "The Clinic B’s manager also voiced that effective implementation of the insulin PDA would depend on the diabetes MO in-charge of diabetes in the clinic." (PMID 33378349, 2020). "Model 3 includes 9 variables: waist circumference, BMI, TG, ALT, AST, fasting glucose, fasting insulin, alcohol consumption, and diabetes status." (PMID 32559194, 2020).